SOCS2 (suppressor of cytokine signaling 2)
Diseases named in the same sentence as SOCS2 in open-access papers (continued):
Sharing a sentence is not in itself a finding about the gene and the disease.
inflammation (3 papers, 2018 to 2024). Aberrant reaction of the microcirculation characterized by movement of fluid and leukocytes from the blood into extravascular tissues. "The current study observed that endometrial inflammation significantly increased the expression of the Prlr gene (p < 0.01) and Socs2 (p < 0.05) in the uterine tissues of mice after LPS treatment." (PMID 39062636, 2024). "This difference in crypt damage/regeneration between genotypes following DSS treatment was not sufficient, however, to alter total pathology scores, indicating that the absence of Socs2 was unable to confer overall protection against DSS-induced gut inflammation." (PMID 29343614, 2018).
cardiovascular diseases (1 paper, 2024). "Through computational analyses and in silico modeling, we aimed to evaluate the effectiveness and specificity of these compounds in modulating SOCS2 function and alleviating the pathological mechanisms associated with cardiovascular diseases." (PMID 39409145, 2024). "This research employed a comprehensive approach to explore the interactions between SOCS2 and proteins and peptides sourced from Lumbricus earthworms, focusing particularly on their potential therapeutic implications in cardiovascular diseases." (PMID 39409145, 2024). "These values compare favorably with the binding affinities of the standard agonist and antagonist, underscoring the potential of these Lumbricus-derived compounds as effective modulators of SOCS2 activity for addressing cardiovascular diseases." (PMID 39409145, 2024). "These values suggest strong binding affinities between these proteins and SOCS2, reinforcing their potential therapeutic efficacy in cardiovascular diseases." (PMID 39409145, 2024). "This research explored the intricate interactions between SOCS2 and proteins derived from Lumbricus earthworms using protein–protein docking simulations, aiming to identify potential therapeutic strategies for cardiovascular diseases." (PMID 39409145, 2024). "In conclusion, this study conducted a thorough investigation into the interactions between Lumbricus-derived proteins and SOCS2, revealing their potential therapeutic implications for cardiovascular diseases." (PMID 39409145, 2024). "The findings indicated that certain proteins such as Lumbricin, Chemoattractive glycoprotein ES20, and Lumbrokinase-7T1 demonstrated activity comparable to standard antagonists in regulating SOCS2 function, suggesting their candidacy for therapeutic applications in cardiovascular diseases." (PMID 39409145, 2024). "Besides focusing on SOCS2, natural products have attracted growing interest as reservoirs of bioactive compounds with therapeutic promise against cardiovascular diseases." (PMID 39409145, 2024).
immune disorders (1 paper, 2024). "The authors proposed SOCS2 inhibitors as attractive chemical probes for studying SOCS2 biology by assessing the downstream effects of SOCS2 inhibition on multiple disease phenotypes and immune disorders." (PMID 39676878, 2024).
infectious disease (1 paper, 2016). A disorder directly resulting from the presence and activity of a microbial, viral, or parasitic agent in humans. "More importantly, v-maf avian musculoaponeurotic fibrosarcoma oncogene homolog B (MAFB), suppressor of cytokine signaling 2 (SOCS2) were found to be associated with SNP rs2057178 in infectious diseases." (PMID 27035414, 2016).
SOCS2 also shares sentences with these, for which no sentence is quoted: Allergy (3 papers); COVID-19 (3); adenocarcinoma (2); alcoholic steatohepatitis (2); anal carcinoma (2); cervical cancer (2); head and neck squamous cell carcinoma (2); lymphoma (2); AIDS (1); and behavioral disorders (1); atherosclerosis (1); atopic dermatitis (1); cerebral malaria (1); cerebrovascular diseases (1); cervical squamous cell carcinoma (1); colonic polyps (1); Crohn disease (1); fibrosis (1); gestational diabetes (1); Glucose intolerance (1); Hypertension (1); Impaired glucose tolerance (1); inflammatory bowel disease (1); lung adenocarcinoma (1); malaria (1); mastocytosis (1); metabolic syndrome (1); metastatic melanoma (1); myelodysplastic syndrome (1); Myocardial fibrosis (1).
A further 12 diseases each share a sentence with SOCS2 in 1 paper.